TRBJ1-2 (T cell receptor beta joining 1-2)
Description:
J region of the variable domain of T cell receptor (TR) beta chain that participates in the antigen recognition. Alpha-beta T cell receptors are antigen specific receptors which are essential to the immune response and are present on the cell surface of T lymphocytes. Recognize peptide-major histocompatibility (MH) (pMH) complexes that are displayed by antigen presenting cells (APC), a prerequisite for efficient T cell adaptive immunity against pathogens. Binding of alpha-beta TR to pMH complex initiates TR-CD3 clustering on the cell surface and intracellular activation of LCK that phosphorylates the ITAM motifs of CD3G, CD3D, CD3E and CD247 enabling the recruitment of ZAP70. In turn ZAP70 phosphorylates LAT, which recruits numerous signaling molecules to form the LAT signalosome. The LAT signalosome propagates signal branching to three major signaling pathways, the calcium, the mitogen-activated protein kinase (MAPK) kinase and the nuclear factor NF-kappa-B (NF-kB) pathways, leading to the mobilization of transcription factors that are critical for gene expression and essential for T cell growth and differentiation. The T cell repertoire is generated in the thymus, by V-(D)-J rearrangement. This repertoire is then shaped by intrathymic selection events to generate a peripheral T cell pool of self-MH restricted, non-autoaggressive T cells. Post-thymic interaction of alpha-beta TR with the pMH complexes shapes TR structural and functional avidity.
Synonyms: TRBJ12; TCRBJ1S2
Gene: T-cell receptor joining (J) gene on chromosome 7 (142,787,017 to 142,787,064, forward strand). Ensembl gene ENSG00000282420.
Subcellular location: Cell membrane
Gene Ontology:
Cellular component: plasma membrane